SNORA33 (small nucleolar RNA, H/ACA box 33)
Synonyms: ACA33
Gene: Small nucleolar RNA gene on chromosome 6 (132,817,219 to 132,817,348, forward strand). Ensembl gene ENSG00000200534.
Gene Ontology:
Biological process: RNA processing
Cellular component: nucleolus
Homologues: Orthologues: chimpanzee SNORA33 (99% identical), macaque SNORA33 (98% identical), rabbit SNORA33 (87% identical).
Diseases named in the same sentence as SNORA33 in open-access papers:
SNORA33 is named in the same sentence as 3 diseases in open-access papers, as found by Europe PMC text mining. Sharing a sentence is not in itself a finding about the gene and the disease. The quoted sentences say what the papers report.
osteoarthritis (1 paper, 2023). A noninflammatory degenerative joint disease occurring chiefly in older persons, characterized by degeneration of the articular cartilage, hypertrophy of bone at the margins and changes in the synovial membrane. "The downregulation of factors attenuating cellular inflammatory responses in SNORA33-depleted cells suggests that ribosome heterogeneity and the loss of 28S-ψ4966 promote chondrocyte inflammatory responses in osteoarthritis." (PMID 37628759, 2023).
scoliosis (1 paper, 2025). A congenital or acquired spinal deformity characterized by lateral curvature of the spine. "SNHG14, SNORA33, NET1, and SNORD100 shared the same variant with HLA DR on CD14+ CD16+ monocyte which could decrease the risk of scoliosis." (PMID 40177401, 2025).
SNORA33 also shares sentences with these, for which no sentence is quoted: cancer (1 paper).